ARF1 (ARF GTPase 1)
Diseases named in the same sentence as ARF1 in open-access papers (continued):
Sharing a sentence is not in itself a finding about the gene and the disease.
infection (continued). "In contrast, upon infection of D. discoideum producing 2×PHFAPP-mCherry and Arf1-GFP with L. pneumophila ΔicmT, the Golgi membranes were inevitably brought into proximity of the compartment harboring the bacteria but did not engage in sustained interactions." (PMID 30538188, 2018). "Previous work showed that ectopically expressed CT813 coimmunoprecipitates with ARF1 and that green fluorescent protein (GFP)-tagged ARF GTPases are recruited around the inclusion in a CT813-dependent manner during infection." (PMID 28465429, 2017). "Based on these findings, we conclude that CT813 specifically interacts with and recruits ARF1 and ARF4 to the inclusion membrane during infection." (PMID 28465429, 2017). "At 24 h post-infection, depletion of GBF1 exerted partial inhibition viral RNA replication, although siRNA specific to ARF1 or GBF1 was functionally active." (PMID 28303920, 2017). "Only ARF1 and ARF4 coimmunoprecipitated with CT813 in CT813-FLAG-tagged Chlamydia-infected cells, demonstrating that the interaction occurs during infection and confirming its specificity." (PMID 28465429, 2017). "BFA inhibits HCV replication when added at the time of or shortly after infection but is less effective at inhibiting replication after infection has been established, suggesting that GBF1 and ARF1 act early in the viral lifecycle." (PMID 22022594, 2011). "SV40 infection is strongly inhibited by expression of GTP-restricted Arf1 and Sar1 mutants and by microinjection of antibodies to β-COP, suggesting that infection requires COP-I-dependent transport steps for successful infection." (PMID 16603059, 2006). "We next studied the localization of Arf1, Arf4, and GBF1 during P. berghei liver stage infection." (PMID 38349168, 2024). "In this study, we firstly confirmed that the piscine ARF1 was recruited by NS80 and NS38 of GCRV into cytoplasmic VIBs via protein-protein interactions, and promoted GCRV replication and infection through facilitating the entry and proliferation processes of GCRV lifecycle." (PMID 36091067, 2022). "The Chlamydia virulence pathway is most similar to that utilized by Salmonella since Chlamydia activates rather than inhibits the ARF1-RhoA network to promote successful infection." (PMID 34903051, 2021). "ARF1, BIN1, RAB7L1, and RAB8A are required for HIV-1 trans-infection." (PMID 32075937, 2020). "Finally, we determined the localization of CT813-recruited ARF1 and ARF4 during infection by using cells transfected with low levels of hemagglutinin (HA)-tagged ARF1 and ARF4." (PMID 28465429, 2017). "Finally, we investigated the contribution of ARF1 and ARF4 to the formation of PTM MT cages during infection." (PMID 28465429, 2017). "Furthermore, we discovered that the presence of RhoA downregulates ARF1 activation, while ARF1-GTP inhibits RhoA activation, highlighting cross talk between two small GTPases to coordinate PTM-MT and actin scaffolds during infection." (PMID 34903051, 2021). "The elution peaks of GBF1 and ARF1 has not changed after EV71 infection compared to mock infection." (PMID 28303920, 2017). "Survival of flies depleted of ARF1 in the trachea is reduced with or without infection." (PMID 28273919, 2017). "However, increased AMP levels in ARF1 knockdown do not provide additional ability to combat infection." (PMID 28273919, 2017). "For Legionella producing RpRalF1–342SS the highest percentage of vacuoles having detectable levels of Arf1-GFP were observed at 30 min post-infection, and Arf1-GFP levels then began to drop to the point where almost no Arf1-GFP staining was observed on vacuoles after 4 hours of infection." (PMID 23166491, 2012). "Thus, while GBF1 might play a role during infection, its function appears to be independent of Arf1." (PMID 38349168, 2024).
infection (continued). "Note that Golgi complex morphology in noninfected cells is not affected by ARF1- or ARF4-siRNA treatment, suggesting that the effect observed during infection is not due to a global Golgi complex defect (data not shown)." (PMID 28465429, 2017). "In contrast, the Golgi complex remained compact in either ARF1 or ARF4 siRNA-treated cells (ARF1 siRNA and ARF4 siRNA), demonstrating that both ARF isoforms are involved in Golgi complex positioning during infection and that their functions are not redundant." (PMID 28465429, 2017).
bacterial infection (3 papers, 2017 to 2023). "Further, perturbation of the ARF1-Asrij axis results in aberrant AMP production and compromises the response to bacterial infection." (PMID 28273919, 2017). "Interestingly, two of the genes that are responsible for the enrichment of bacterial infection (Salmonella, Vibrio cholerae and Escherichia coli) pathways are ACTB and ARF1." (PMID 37243274, 2023).
neurodegenerative disease (3 papers, 2014 to 2025). A disorder of the central nervous system characterized by gradual and progressive loss of neural tissue and neurologic function. "As drugs are being developed for other GTPases, ARF1 or Cdc42 are potentially suitable targets for therapeutic development for JNCL, a currently untreatable, fatal neurodegenerative disease." (PMID 24792215, 2014).
neurologic disease (2 papers, 2016 to 2023). "The ablation of Arf1 in neurons through a focused approach resulted in a pronounced phenotype of neurological disorder." (PMID 38239560, 2023).
infectious disease (1 paper, 2023). A disorder directly resulting from the presence and activity of a microbial, viral, or parasitic agent in humans. "Future studies dissecting the different functions of ARF1 in the regulation of the IFN response to infectious diseases, and the molecular mechanism by which ARF1 maintains mitochondrial integrity, are warranted." (PMID 37914730, 2023).
prostate (1 paper, 2016). "Our data provide direct evidence implicating that ARF1-mediated Raf1/MEK/ERK1/2 signaling is critical for prostate tumorigenesis and that genetic approaches targeting ARF1 in animal models may provide an important and novel avenue for studying tumorigenesis and developing therapeutics." (PMID 27213581, 2016).
ARF1 also shares sentences with these, for which no sentence is quoted: Intellectual disability (3 papers); developmental delay (2); malaria (2); metastatic tumors (2); multiple sclerosis (2); Periventricular heterotopia (2); Alzheimer disease (1); B-cell lymphoma (1); Cerebral atrophy (1); Chorea (1); enterovirus infection (1); epilepsy (1); escherichia coli infection (1); esophageal carcinoma (1); gastrinomas (1); Insulin resistance (1); leukemia (1); lipid metabolic disorder (1); lung diseases (1); multiple myeloma (1); neuroendocrine tumour (1); neuronal migration disorder (1); osteoarthritis (1); pancreatic ductal adenocarcinoma (1); pancreatic insulinoma (1); polio (1); prostate adenocarcinoma (1); prostate tumors (1); retinal degeneration (1); skin cutaneous melanoma (1).
A further 2 diseases each share a sentence with ARF1 in 1 paper.